RNU6-576P (RNA, U6 small nuclear 576, pseudogene)
Gene: Small nuclear RNA gene on chromosome 10 (2,199,387 to 2,199,488, forward strand). Ensembl gene ENSG00000212156.
Homologues: Orthologues: chimpanzee U6 (100% identical), macaque U6 (90% identical), dog U6 (71% identical), pig U6 (70% identical), guinea pig U6 (67% identical), pig U6 (66% identical), rabbit U6 (66% identical). Paralogues in human: RNU6-140P (78% identical), RNU6-16P (78% identical), RNU6-20P (78% identical), RNU6-246P (78% identical), RNU6-35P (78% identical), RNU6-434P (78% identical), RNU6-1152P (77% identical), RNU6-211P (77% identical), RNU6-25P (77% identical), RNU6-29P (77% identical), RNU6-33P (77% identical), RNU6-536P (77% identical), and 1287 more.